CRP (C-reactive protein)
Diseases named in the same sentence as CRP in open-access papers (continued):
Sharing a sentence is not in itself a finding about the gene and the disease.
hypophosphatemia (12 papers, 2021 to 2026). Lower than normal levels of phosphates in the circulating blood. "Laboratory investigations showed hypophosphatemia, elevated renal phosphate loss, and raised inflammatory markers (CRP (C-reactive protein) and granulocytes)." (PMID 41597024, 2025). "Elevated CRP, liver transaminases, and prolonged hospitalization were also more pronounced in patients with hypophosphatemia, reinforcing its potential as a marker of severity." (PMID 41416290, 2025). "Patients with hypophosphatemia were likely to be older and with lower lymphocyte count, lower serum albumin and uric acid levels, higher LDH, and CRP levels." (PMID 34541999, 2021). "Patients with hypophosphatemia were likely to be older and with lower lymphocyte count, lower serum albumin level, lower uric acid, higher LDH, and higher CRP." (PMID 34541999, 2021). "The prevalence of hypophosphatemia and inflammation (measured by CRP) did no differ between groups." (PMID 39762420, 2025). "Our results show that patients with hypophosphatemia had lower lymphocyte count, higher aspartate aminotransferase, longer prothrombin time, higher CRP and LDH levels, which suggests that hypophosphatemia may have been related to disease severity and multiple organ injuries." (PMID 34541999, 2021).
intrauterine growth restriction (12 papers, 2009 to 2025). "Therefore, in our cases, elevated levels of CRP in LGA and SGA children could be a consequence of oxidative stress and intrauterine growth restriction, respectively; both conditions reported to be related to excessive production of cytokines, including CRP." (PMID 24659848, 2014).
lactic acidosis (12 papers, 2013 to 2025). Metabolic acidosis characterized by the accumulation of lactate in the body. "SCD treatments were then re-initiated on HAD 9 and treatment with the SCD was associated with declines in C-reactive protein (CRP) and procalcitonin along with resolution of his lactic acidosis." (PMID 40542849, 2025). "Systemic inflammatory markers (e.g., C-reactive protein (CRP), pro-inflammatory cytokine, Interleukin-6 (IL-6), and lactic acidosis frequently indicate systemic involvement and intestinal ischemia." (PMID 41007847, 2025).
monocytopenia (12 papers, 2019 to 2025). "One study found that HLH secondary to VL was associated with higher inflammatory markers such as CRP and monocytopenia compared to uncomplicated VL." (PMID 41142222, 2025). "The average CRP levels in these instances were recorded at 65.6 ± 132.8 mg/L, and monocytopenia showed a mean value of 2.3 ± 2.3%." (PMID 41210881, 2025). "These suggested that in patients with very poor baseline conditions (old age, co-CVDs, and SCAP), hypothermia, monocytopenia or elevated levels of acute inflammatory markers (NLR and CRP) represented a poor prognosis." (PMID 35964040, 2022).
Myocardial necrosis (12 papers, 2009 to 2025). Irreversible damage to heart tissue (myocardium) due to lack of oxygen after a heart attack (myocardial infarction). "CRP and CP were associated with subclinical myocardial necrosis after 3-years of follow-up." (PMID 33096845, 2020). "Collectively, these findings reinforce the pathophysiological and prognostic roles of ventricular dysfunction (LVEF), myocardial necrosis (CK-MB), and systemic inflammation (hs-CRP) in AMI-CS mortality." (PMID 41179560, 2025). "Laboratory diagnostics include myocardial necrosis markers such as high-sensitivity troponins and creatinine kinase-MB, with inflammatory markers such as elevated C-reactive protein and erythrocyte sedimentation rate also frequently observed." (PMID 39410640, 2024). "Furthermore, fibrosis was not correlated with LV wall thickness, diameters, and volumes as well as EF, blood markers of myocardial necrosis (CK, CK-MB, troponin), marker of inflammation (hs-CRP) or myocardial strain (NT-proBNP)." (PMID 27516211, 2016). "We used peak CRP since it might better reflect the magnitude of the inflammatory response to myocardial necrosis, which we hypothesized would have an impact on platelet reactivity." (PMID 19583836, 2009). "Therefore, combining these data with our results, we and other authors believe that CRP might be a simple and reliable marker for the magnitude of the inflammatory response to myocardial necrosis, providing prognostic information in STEMI patients." (PMID 22446726, 2012).
otitis (12 papers, 2013 to 2026). "In our study, we identified that, unsurprisingly, increased white blood cell counts, particularly increased neutrophil counts, along with increased ESR and CRP, are more commonly associated with APOM compared to other types of otitis." (PMID 39062281, 2024). "A statistically significant relationship was found between the diagnosis of otitis and immunoglobulin E and CRP levels." (PMID 39846516, 2024). "The univariate logistic regression model showed that CRP has a statistically significant effect in predicting otitis (p-value = 0.011) with every unit increase in the CRP levels resulting in a 3% increase in the odds of being diagnosed with otitis." (PMID 39846516, 2024).
panic disorder (12 papers, 2008 to 2025). An anxiety disorder characterized by multiple unexpected panic attacks with persistent concern of recurring attacks. "The existing findings indicate that GAD and panic disorders (PD) in particular are associated with a pro-inflammatory state, which is evidenced by elevated peripheral cytokines and CRP concentrations in these diseases." (PMID 38563030, 2024).
pertussis (12 papers, 2006 to 2026). A contagious bacterial respiratory infection caused by Bordetella pertussis. "While PCT and high-sensitivity C-reactive protein (hs-CRP) are commonly used biomarkers for auxiliary diagnosis of infectious diseases, only a few studies have assessed their diagnostic value in pertussis diagnosis." (PMID 41479551, 2025). "While fever is uncommon in pertussis, the condition is often associated with elevated levels of neutrophils, C-reactive protein (CRP), and procalcitonin, indicating the possible presence of concurrent bacterial infections." (PMID 40426495, 2025). "Lymphocyte counts (H = 178.03) were the highest in the pertussis-only group, and neutrophil counts (H = 119.45) and C-reactive protein (H = 369.80) were the highest in the MP-only group (all p<0.001)." (PMID 41835008, 2026). "Before ET, CRP and PCT levels in the mortality group were higher than those in the surviving group, suggesting that the immunity of pertussis patients was weakened and their susceptibility to pathogens increased." (PMID 41044722, 2025). "Our results demonstrate that children with pertussis exhibit significantly higher CRP levels and WBC counts and prolonged hospitalization compared to controls." (PMID 40539153, 2025). "Recent studies have indicated that when infants with severe pertussis have a body temperature ≥ 38.5 °C, CRP > 30 mg/L, and WBC > 40.0 × 109/L, ET should be considered." (PMID 41044722, 2025). "While the CRP level is often normal or only mildly elevated in typical pertussis cases, recent studies have shown that elevated CRP levels may be associated with more severe presentations, including those requiring ICU admission and exchange transfusion." (PMID 40710034, 2025). "The mean hospital stay length, C-reactive protein (CRP), and white blood cell (WBC) count were significantly higher in the pertussis group." (PMID 40539153, 2025). "Unlike a parenterally delivered whole-cell pertussis vaccine, which induced high levels of serum IL-1β, IL-6, tumour necrosis factor and C-reactive protein, aerosol immunization with the AIBP vaccine did not promote systemic pro-inflammatory responses." (PMID 41214155, 2025). "Raised CRP concentrations have been reported in infants/children with severe pertussis, and old data have demonstrated that not all psittacosis had elevated CRP values, yet further data are limited." (PMID 37873776, 2023). "We investigated the prevalence and clinical characteristics, CRP and peripheral white cell count indices of pertussis in children irrespective of the cough duration." (PMID 31299934, 2019). "Our study’s primary aim was to compare the similarities and differences in the clinical features, microbiology, CRP and peripheral white blood cell count indices among 312 children with acute, sub-acute or chronic cough, with and without pertussis." (PMID 31299934, 2019). "This differs from a previous study in preterm infants where increased adverse cardiorespiratory events and increased systemic inflammatory markers (IL-6, CRP) occurred in 30% of infants receiving whole cell pertussis vaccine but in no infants receiving acellular pertussis vaccine." (PMID 16784533, 2006). "Notably, while CRP and WBC are nonspecific markers of infection, their elevation in pertussis cases supports their utility in differentiating pertussis from other respiratory illnesses, especially in resource-limited settings where molecular diagnostics are unavailable." (PMID 40539153, 2025).
Pleuritis (12 papers, 2011 to 2025). Inflammation of the pleura. "We assessed the levels of ferritin, CRP, and ADA in unstimulated plasma of TB lymphadenitis and pleuritis patients at baseline and changes in their levels with anti-TB treatment to see their utility as biomarkers to monitor treatment response." (PMID 39623309, 2024). "Before the start of treatment, plasma levels of ferritin were raised in 13% and 45%, CRP in 21% and 64%, and ADA in 70% and 60% of TB lymphadenitis and pleuritis cases respectively." (PMID 39623309, 2024). "None of the current serum (eg CRP or ESR) or pleural fluid markers (eg LDH, protein, pH, cell counts) can reliably discriminate pleural infection reliably from non-infective (eg malignant, rheumatoid or drug) pleuritis." (PMID 23251353, 2012).
respiratory distress syndrome (12 papers, 2015 to 2025). "Prematurity, respiratory distress syndrome due to surfactant deficiency, and normal initially C-reactive protein values had an important contribution in delaying CSC diagnosis." (PMID 39338543, 2024). "Our results indicated that prolonged rupture of membranes and high CRP values significantly increased the risk of the composite outcome 1 occurrence (Apgar score < 7 at 1 min of birth + respiratory distress syndrome + non-invasive ventilation) in the evaluated cohort." (PMID 39857097, 2025). "Most of these had respiratory distress syndrome, increased CRP, and antibiotic treatment, so they met the criteria to be finally classified as cases of probable infection." (PMID 38721478, 2024). "The naive Bayesian learnt that preterm birth, C-reactive protein, neonatal growth restriction, neonatal respiratory distress syndrome, amniotic fluid volume and premature rupture of membranes have a greater impact on the outcome of neonatal pneumonia." (PMID 37880592, 2023). "At the time of diagnosis of NEC, the expression of SIRT1 decreased in children with respiratory distress syndrome and CRP level increased." (PMID 35958178, 2022). "CRP, the main ARP, is increased not only by bacterial infection but also in the settings of various pathologies, for example, respiratory distress syndrome, asphyxia neonatorum, and meconium aspiration syndrome." (PMID 25667565, 2015). "Its levels increase more rapidly and may be more useful for detection of EOS as compared with CRP but it may also increase with noninfectious causes such as respiratory distress syndrome, trauma, and major and cardiac surgery and physiologically during the first 24 hours of birth." (PMID 26380313, 2015).
skin infection (12 papers, 2014 to 2025). An inflammatory process affecting the skin, caused by bacteria, viruses, parasites, or fungi. "Patients with various infections such as respiratory, urinary, or skin infections, with an initial CRP level > 100 mg/L, and CRP < 100 mg/L after treatment, were included." (PMID 39062061, 2024). "Acute phase reactants, such as ESR and CRP, have been used regularly in clinical practice in the workup of skin infections and even showed good results in predicting the severity of such conditions." (PMID 38978890, 2024). "The criteria for the oral-only approach were 0.5–3 years of age, good overall condition, oral tolerance, no underlying disease, injury, skin infection, recent surgery, complications, CRP ≤ 80 mg/L, ESR/CRP ratio ≥ 0.67, daily follow-up, and informed consent." (PMID 40868015, 2025). "Among patients with bacterial infection, CRP levels were highest in those with fever without source and lowest with skin infections." (PMID 37478118, 2023). "The commonest diagnostic tests used in RTI were C-reactive protein (66/105, 62.9%) and blood cell count (in 60/105, 57.1% of RTI), the urine dipstick test was performed in 71/83 (85.5%) of UTI cases, whereas for most skin infections (28/48, 58.3%) no diagnostic tests were done." (PMID 30458914, 2018).
subacute thyroiditis (12 papers, 2005 to 2025). Self-limited inflammation of the thyroid gland characterized by the presence of multinucleated giant cells. "Elevated C-reactive protein (CRP) levels, along with clinical signs like thyroid swelling, pain, and tenderness, are often associated with subacute thyroiditis, which appears as hypoechoic areas on ultrasound and stiff on elastography." (PMID 40580400, 2025). "The likelihood of elevated fT4 being secondary to subacute thyroiditis is strengthened by the significantly elevated CRP levels in Gr." (PMID 36231061, 2022). "As shown, Subacute Granulomatous Thyroiditis has a very high inflammatory load with very high ESR and CRP levels, severe clinic, and histological verifications by previous studies." (PMID 32063967, 2020). "In fact, several studies have demonstrated a strong correlation between thyroid function and elevated CRP levels in patients primarily with subacute thyroiditis; this correlation is not necessarily seen in other inflammatory thyroid conditions." (PMID 36231061, 2022). "The clinical features, abnormal thyroid function, raised CRP and negative thyroid antibodies 3 weeks post-MPX positive test was consistent with viral subacute thyroiditis." (PMID 37584380, 2023).
urothelial carcinoma (12 papers, 2013 to 2025). A malignant neoplasm derived from the transitional epithelium of the urinary tract (urinary bladder, ureter, urethra, or renal pelvis). "Elevated pre-treatment NLR, CRP, PLR, and LDH are significantly associated with worse OS and PFS in ICI-treated urothelial carcinoma patients, suggesting that they have potential prognostic and predictive value in treatment decisions." (PMID 40165971, 2025). "CRP kinetics is also a strong prognostic factor in patients with advanced solid tumors, including metastatic renal cell cancer and advanced urothelial carcinoma." (PMID 24130817, 2013). "At time of treatment with chemotherapy for advanced urothelial carcinoma, stratifying patients as non-elevated CRP (57.5% of patients), elevated to normalized CRP (30% of patients), and non-normalized CRP (12.5% of patients) groups held significant prognostic value." (PMID 34512646, 2021).
acute myeloid leukemia (11 papers, 2017 to 2025). Acute myeloid leukemia (AML) is a group of neoplasms arising from precursor cells committed to the myeloid cell-line differentiation. "In the acute myeloid leukemia subset, thrombotic event occurrence was associated with a higher peripheral blast percentage and elevated C-reactive protein levels." (PMID 40994887, 2025). "Again, we observed clear clustering of TGF-β2+Inhibin A/SASP-related enhancer sets with traits linked to chronic inflammation, including C-reactive protein levels, acute myeloid leukemia, and brain aneurysm." (PMID 40493192, 2025). "Advanced disease, one or more co-morbidities, older age, type of malignancy, in particular acute myeloid leukemia (AML), and several laboratory parameters, for example high C-reactive protein, lymphopenia, and neutropenia, were found to be risk factors for COVID-19 in HM patients." (PMID 34649563, 2021). "It is highly probable that other infections than BSI have triggered high CRP and low PA values, as we have shown for numerous CRP peaks and PA troughs that were unrelated to BSI episodes in patients with acute myeloid leukaemia." (PMID 35238275, 2022). "A recent report on acute myeloid leukemia patients not eligible for stem-cell transplantation illustrates that a combined assessment of CRP and albumin is of interest in myeloid malignancies in general." (PMID 36900271, 2023). "No study has evaluated C-reactive protein (CRP) and plasma albumin (PA) levels longitudinally in patients with acute myeloid leukaemia (AML)." (PMID 32209087, 2020).
ANCA-associated vasculitis (11 papers, 2015 to 2025). "In addition, CRP is found capable of enhancing the activation of the coagulation cascade and potentiating an inflammatory response by dissociating into monomeric form in case of antineutrophil cytoplasmic antibody-associated vasculitis." (PMID 33188660, 2020). "The heatmap presents the responsiveness of the key biomarkers—CRP, ESR, BVAS, eGFR, and albuminuria—in nine milestone trials evaluating new treatments for ANCA-associated vasculitis." (PMID 41044670, 2025).
Arthralgia (11 papers, 2014 to 2025). "We found that moderate to severe arthralgia is associated with specific serum markers of inflammation (elevated CRP, eotaxin, MCP-1, and VDBP) among women taking AIs." (PMID 26126656, 2015). "Furthermore, we evaluated whether the degree of inflammation visualised on MRI scans of ACPA-negative arthralgia patients was associated with the level of serological inflammation as measured by CRP levels." (PMID 24721160, 2014). "When FDRs with arthralgia were compared to those who were asymptomatic, several observations were done: FDRs with arthralgia had significantly higher ESR and CRP than asymptomatic FDRs (both p = 0.003)." (PMID 38443806, 2024). "Arthralgia (OR 4.90, p = 0.0012), DO of PET/CT (OR 4.09, p = 0.016), CRP > 30 mg/L (OR 3.70, p = 0.033), and chills (OR 3.06, p = 0.0248) were associated with the achievement of a diagnosis (Se: 89.1%, Sp: 56.8%)." (PMID 35054081, 2022). "Unspecific inflammatory parameters were found in 79% of patients with BRAFi-induced arthralgia, as found for almost three-quarters of ICI-treated patients with irAEs showing elevated CRP levels." (PMID 33081201, 2020). "Moreover, FDRs with arthralgia experience higher mean levels of serum OPN, OPG, ESR, CRP, RF, and ACPA than asymptomatic FDRs." (PMID 38443806, 2024).
atopic dermatitis (11 papers, 2017 to 2025). "Several blood molecules have been investigated in human studies as potential biomarkers of atopic dermatitis, including TARC/CCL17, macrophage-derived chemokine, IL-22, pulmonary and activation-regulated chemokine, sIL-2R, soluble E-selectin, C-reactive protein, and IL-16." (PMID 34677385, 2021).
chronic spontaneous urticaria (11 papers, 2013 to 2026). "Little correlation was demonstrated between the severity of chronic spontaneous urticaria and the levels of C-reactive protein." (PMID 33640190, 2021). "Among those, CRP is one of the major proteins helpful in determination of severity/activity of chronic spontaneous urticaria (CSU)." (PMID 25025065, 2014). "Chronic spontaneous urticaria patients with increased C-reactive protein (CRP) levels also may exhibit increased D-dimer levels, IL-6, C3 and C4 levels, more severe CSU activity and autologous serum skin test positivity consistent with type 2b autoimmune CSU." (PMID 40546743, 2025). "Systemic inflammatory markers, particularly C-reactive protein (CRP) and erythrocyte sedimentation rate (ESR), have gained attention as potential prognostic indicators in chronic spontaneous urticaria." (PMID 41608596, 2026). "According to the current international guideline, a differential blood count and C-reactive protein (CRP) and/or erythrocyte sedimentation rate (ESR) are recommended as basic screening tests in patients with chronic spontaneous urticaria." (PMID 36644011, 2023).